IL1B (interleukin 1 beta)
Diseases named in the same sentence as IL1B in open-access papers (continued):
Sharing a sentence is not in itself a finding about the gene and the disease.
infection (continued). "In this study, we found that macrophage infection with LgyLRV1+ parasites resulted in the transcriptional up-regulation of several inflammasome components such as caspase-1, IL-1β, NLRP3, and AIM2." (PMID 29487860, 2018). "Their hippocampal levels of the proinflammatory cytokine IL-1β are significantly elevated for at least 8 d, but generally less than 14 d, after infection or surgery." (PMID 29911174, 2018). "Compared to ST6, infection with ST1 led initially to higher levels of IL-1β and TNF-α in blood and more profound neuropathological damage." (PMID 30193592, 2018). "In some infections by airborne pathogens, IL-1β produced by alveolar macrophages has been shown to induce the secretion of neutrophils chemoattractants by lung epithelial cells." (PMID 30456207, 2018). "Apart from the ATP-induced pathway typical for trauma-associated sterile inflammation, several alternative mechanisms of IL-1β maturation are activated during infection." (PMID 30105015, 2018). "Analysis of gene expression in whole brain confirmed infection triggered CNS inflammation by showing upregulation of mRNA for IL-1β, TNF, and IFN-γ." (PMID 30538705, 2018). "Consistent with in vitro observation, when mice were infected with the A28006 strain, we observed higher levels of IL-1β than we observed in pulmonary A54970 infection." (PMID 30518854, 2018). "These include intraventricular and hippocampal IL-1 administration, multiweek elevation of IL-1β in the hippocampi of transgenic mice, and elevation of endogenous IL-1β evoked by infections or psychological stressors." (PMID 29911174, 2018). "It has been documented that ExoY lowers concentrations of TNF and IL-1β after infection of rat lungs or epithelial cells, respectively." (PMID 29734720, 2018). "Except at 1 d and 42 d post-infection, the IL-1β concentration in the infection group was significantly higher than that in the blank group, which maintained a low level with no fluctuations." (PMID 29490620, 2018). "In sera, only the peak concentrations of Cxcl1 (8 h), Ccl2 (8 h), Ccl3 (8 h), IL-1β (4 h), and IL-6 (4–8 h after infection) were significantly elevated in ExoY-infected mice as compared to ExoYK81M-infected mice." (PMID 29734720, 2018). "Lesion formation was monitored at 24, 48, and 72 h post-infection, and at 72 h post-infection, the mice were sacrificed and plasma samples as well as the skin tissue surrounding the infection site were harvested for IL-1β analysis." (PMID 30018884, 2018). "In the supernatant of this infection condition, secreted IL-1β was detectable at 2 h and increased in a time-dependent manner." (PMID 29667111, 2018). "IL1B experimentally administrated to the brain as well as released in the periphery during infection can elicit vertebrate sickness behaviors and impair memory." (PMID 29403495, 2018). "Inhibiting the activity of IL-1β during infection reduced SLS-mediated lesion pathology in an animal model." (PMID 30018884, 2018). "Localized S. aureus infection of the skin in Il1b−/− mice resulted in poor bacterial control during primary infection but protection against reinfection, revealing the potential presence of an additional memory γδ T cell subset." (PMID 30538697, 2018). "IL-1β mRNA levels were upregulated throughout the time course in response to infection with both M. bovis strains." (PMID 29263113, 2018). "We determine that infected murine microglia produce several pro-inflammatory cytokines as the result of direct infection, including IFNγ, IL-1α, IL-1β, IL-6, and IL-12." (PMID 30400156, 2018). "An ELISA was performed to quantify the amount of IL-1β being produced under each infection condition." (PMID 30018884, 2018). "Subcutaneous infection studies were performed in mice to address the physiological impact of increased IL-1β production." (PMID 30018884, 2018).
infection (continued). "Infection with the fpt mutant strain elicited altered inflammatory cytokine secretion: F. tularensis SchuS4ΔfptB infection resulted in a 12-h delay in IL-1β secretion and a significantly reduced TNF-α response across all time points measured." (PMID 29311235, 2018). "In this study, we examined later time points—8 and 14 d after injection—to determine if levels of mBDNF in aged animals would recover as levels of IL-1β dropped toward pre-infection baselines." (PMID 29911174, 2018). "Mice exposed to the infection also had a significant increase in the expression of IL-1β (main effect of infection, p<0.05)." (PMID 29742146, 2018). "Infection with Mtb bacilli is known to induce IL-1β both through inflammasome- (NLRP3) dependent and independent pathways." (PMID 29740038, 2018). "Morphologically, cells do not appear to lyse as would be expected from necrosis or pyroptosis (though IL-1β is released during infections)." (PMID 30524442, 2018). "The effect of infection on the drug metabolizing enzymes is carried by the few cytokines such as IL-1β, IL6, tumor necrosis factor alpha (TNF-α), and interferon (INF) α or γ." (PMID 29849489, 2018). "Another group showed that blockade of IL-1β signalling rendered BALB/c mice resistant to the infection." (PMID 29487860, 2018). "Inflammasomes, which are activated by cell infection and stress, have the potential to trigger the activation of caspase-1, which cleaves the pro-IL-1β and IL-18 into their mature forms, resulting in IL-1β and IL-18 secretion." (PMID 29773990, 2018). "IL-1β is a major pro-inflammatory cytokine generated in response to infection, which contributes to tissue injury during disease." (PMID 29290552, 2018). "The mature caspase-1 then proteolytically cleaves cytosolic pro-IL-1β and pro-IL-18, which are subsequently secreted as inflammatory cytokines that activate the inflammatory arm of the immune response to infection." (PMID 30013955, 2018). "Experimental infection of a commercial broiler line A1 elicits expression of the pro-inflammatory chemokines CXCLi1, CXCLi2 and IL-1β in the ceca at 2 and 5 days post-infection." (PMID 29316981, 2018). "In particular, IL-1β is known to have a central role in the pulmonary immune response to inhaled pathogens during the first days after infection, which was the time frame addressed in the present study." (PMID 30456207, 2018). "b Bar plot depicting the pro-IL-1β/α-Tubulin ratio as determined by densitometric analysis of Western blotting and expressed as fold change compared with the mock-infection control." (PMID 29291748, 2018). "In this study, we show that free extracellular ISG15 is produced and released in a type I IFN–dependent fashion and enhances IFN-γ and IL-1β levels during infection with live replicative Toxoplasma type II." (PMID 29891555, 2018). "And various studies show that inflammasome-mediated IL-18 or IL-1β plays important roles in controlling pathogens and promoting adaptive immune response against infection." (PMID 30105037, 2018). "Infection induced a dimorphic pattern, particularly in sham-infected animals; females exhibited significantly decreased IL-1β expression compared with that in sham, intact, and uninfected mice, and the opposite effect was detected in males (P < 0.001)." (PMID 30515051, 2018). "The treatment with Mdivi-1 led to a decreased IL-1β production upon Sk02 infection in a dose-dependent manner." (PMID 30096906, 2018). "The cysteine residues of free ISG15 are required to trigger an increase in CD8α+ DCs producing IL-1β at the site of the infection." (PMID 29891555, 2018). "In order to confirm that Pb was responsible for the severity of the symptoms, artificial conditions imitating the infection were created by administering IL-1b and/or IL-6 directly to the mice." (PMID 29925772, 2018). "We observed a trend towards increased levels of TNFα, IL-6, IL-1β, and IL-1α in the lung tissue of p110δE1020K-GL mice at 24 h post-infection." (PMID 30093657, 2018).
infection (continued). "Interleukin (IL)-1β is a potent pro-inflammatory cytokine that plays a central role in host defense against infections and is mainly produced by monocytes, macrophages, and dendritic cells." (PMID 29922281, 2018). "Our analysis indicates that direct TC-83 infection of microglia results in production of numerous pro-inflammatory cytokines, including IFNγ, IL-1α, IL-1β, and IL12p70." (PMID 30400156, 2018). "Secretion of IL-1β was also measured upon infection since it was suspected to play a role in controlling OPN expression during RSV infection." (PMID 29677209, 2018). "The primary microglia cells experienced a 2.1 pg/mL increase in IL-1α, a 9.72 pg/mL increase in IL-1β, a 35.93 pg/mL increase in IL-6, and a 55.09 pg/mL increase in IL-8 signaling at 2hpi during TC-83 infection." (PMID 30101649, 2018). "There is a report that MRP14 induces the secretion of TNFα, IL-1β and IL-6 dependent on TLR4, and it is also reported that these inflammatory cytokines can be associated with the pathology during infection with P. berghei." (PMID 29902248, 2018). "The development of lesions was observed, and biopsies of the injection site and various organs, including the kidney, liver, spleen, lung, and testis, were obtained for NLRP3, caspase-1, and interleukin-1β (IL-1β) mRNA analysis during infection." (PMID 29490620, 2018). "In contrast, LPS-primed macrophages did show significant secretion of IL-1β upon infection with either CTG or GT1 parasites by 20 h postinfection." (PMID 30154263, 2018). "We found that ISG15 levels correlate with an increase of IL-1β levels in the serum and with increased number and frequency of CD8α+ conventional DCs at the site of infection." (PMID 29891555, 2018). "Conversely, infection of HAECs with Ad.AMPK-DN markedly increased IL-1β-stimulated phosphorylation of JNK." (PMID 29588466, 2018). "PID piglet IL1B expression in liver was approximately double that of PN (diet × infection p = 0.048)." (PMID 30778359, 2018). "Other pro-inflammatory responses that were also elevated in the presence of properdin at initial stages of infection are IL-1β and IL-6." (PMID 29867915, 2018). "In this light, a highly responsive il1β-driven inflammatory response seems to define the behavioural infection phenotype of gilthead sea bream exposed to waterborne Vibrio anguillarum." (PMID 30478379, 2018). "Markers of inflammation, including neutrophil infiltration and proinflammatory cytokine production in the BALF, such as TNF-α, IL-1β and IL-6, were determined 24 h post-infection." (PMID 29875759, 2018). "In a rhesus monkey GBS infection model, increased amniotic fluid TNF-α, IL-1β, and IL-6 occurred before uterine contractility or any clinical signs of infection, suggesting a direct role for infection in triggering preterm labor." (PMID 29520354, 2018). "Increased ISG15 is concurrent with an influx of IL-1β–producing CD8α+ dendritic cells to the site of infection." (PMID 29891555, 2018). "LgyLRV1+ infection or poly(I:C) treatment increased the expression of the pro-form of IL-1β, and thus acted as priming signals." (PMID 29487860, 2018). "IL-1β has been shown to play an important role in the recruitment of neutrophils and other inflammatory cells to sites of infection, which, in most cases, is beneficial to the host for the containment of microbial infections." (PMID 30018884, 2018). "Infection with both strains resulted in dramatically reduced mRNA levels of il1b, tnfa, prostaglandin-endoperoxide synthase 2a (ptgs2a) and ptgs2b compared with fish injected with PBS." (PMID 30143654, 2018). "Recently others reported that pyroptosis leads to secretion of molecules such as IL-1β, IL-1α and eicosanoids which recruit neutrophils to the site of infection promoting phagocytosis of infected cells and contributing to restricting infection." (PMID 30589883, 2018).
infection (continued). "The infection activates PRRs to increase expression of pro-IL-1β that will be transformed into mature and active form of IL-1β by the inflammasome named nod-like receptor family pyrin domain containing-3 (NLRP3)." (PMID 29361942, 2018). "Transcription of inflammatory cytokines (e.g., cxcl, ccl2, 1l1a, and il1b) peaked at 1.5 and 3 h of infection." (PMID 30062089, 2018). "Initially, we monitored IL-1β transcripts and found that infection with T. gondii only slightly altered their levels, while treatment with LPS greatly increased mRNA levels." (PMID 30154263, 2018). "Cytokine release is also a response to HIV proteins, since exposure of macrophages to intact HIV-1 virions or gp120 induced IL-1β release independently of productive infection." (PMID 29256041, 2018). "The observed changes in bacterial numbers in the skin tissue at 24 h post-infection raise interesting questions about the mechanism at play in our studies and highlight the importance of an appropriate balance of IL-1β signaling during GAS infection." (PMID 30018884, 2018). "Treatment of cells with PGE2 prior to infection with S. Typhimurium or Y. enterocolitica did lead to an increase in IL-1β secretion and a decrease in TNF-α secretion." (PMID 30429830, 2018). "While a high production of IL-1β (> 3.104 pg/ml) is indicative of the presence of bacteria in the lungs (mainly ranging from 105−109 bacteria), IL-1β is expressed at intermediate levels (500–3.000 pg/ml) when mice managed to clear the infection." (PMID 29381692, 2018). "The mature caspase 1 proteolytically cleaves cytosolic pro-IL-1β and pro-IL-18, which are then secreted as inflammatory cytokines, which activate the inflammatory arm of the immune response to infection." (PMID 30013955, 2018). "Next, we evaluated IL-12/23p40 and IL-1β production in the spleens of DC_ACC1 and MΦ_ACC1 at different time points after infection." (PMID 29675017, 2018). "Collectively, the current work provides evidence of a novel pathway by which T. gondii manipulates neutrophils, disarming innate immunity by limiting the production of IL-1β during infection, and potentially promoting survival of the parasite." (PMID 29440572, 2018). "This raises the question if concomitant infection increases resistance to IVIG treatment by increasing levels of IL-1β cytokines." (PMID 30332473, 2018). "We also demonstrate that PGE2 increases specific pro-inflammatory cytokines relevant to infection and characteristics of M1 phenotype (mainly IL-1β and IL-23/17) while shifting polarization away from the M2 phenotype." (PMID 30429830, 2018). "Toxoplasma gondii can invade and replicate in all nucleated cells in a wide range of host species, and infection induces IL-1β production." (PMID 29291748, 2018). "Both IL-1β and KC are released by epithelial and immune cells recruited to the site of infection that can exacerbate tissue injury." (PMID 30687644, 2018). "Given the large number of neutrophils recruited to sites of acute T. gondii infection and the importance of IL-1β in immunity and inflammation during infection, we evaluated the secretion of IL-1β into the culture supernatant of infected human neutrophils." (PMID 29440572, 2018). "Regarding pro-inflammatory cytokines, the expression of il-1β after intraperitoneal (i.p.)infection with V. anguillarum has been previously observed at systemic level in gilthead sea bream (Sparus aurata) 4 h after bacterial challenge." (PMID 29867929, 2018). "Infection of FHs 74 Int cells by T. gondii triggered significant time- and dose-dependent IL-1β production." (PMID 29291748, 2018). "First, we quantified the expression of il10, tnfa, tnfb, and il1b in the abdominal organ blocks of zebrafish at early time points during an infection." (PMID 29985419, 2018). "The cytokine production levels of TNF-α, IL-1β, and IL-10 in the cell-free culture supernatants were significantly enhanced in response to S. aureus at 24 h after infection." (PMID 29523806, 2018).
infection (continued). "Robust production of this cytokine by SLS-producing strains of GAS was observed, with significantly reduced IL-1β production in the presence of the ΔsagA mutant or following mock infection." (PMID 30018884, 2018). "Their results showed that serum levels of TNF-α and IFN-α were correlated with hyperthermia, while BALF levels of IL-1β or IL-8 were strongly correlated to clinical score in the Lena-infection group." (PMID 30469357, 2018). "In summary, this study showed that infection with S. mutans triggered caspase-1-dependent IL-1β secretion via activation of the NLRP3, AIM2, and NLRC4 inflammasomes." (PMID 30078841, 2018). "Results from these analyses indicated that sagA complemented GAS induces a 2-fold or greater increase in I-309, IL-1α, IL-1β, IL-2, IL-15, MCP-3, MIG, and MIP-1δ compared to the SLS-deficient mutant infection." (PMID 30018884, 2018). "Inflammasomes can be triggered by infection or stress, and once activated, caspase-1 is responsible for processing the precursors of IL-1β and IL-18 into their mature forms, which are secreted into the extracellular environment." (PMID 29773990, 2018). "At 24 hpi, over 11 times more IL-1β protein was released in response to AF2122 infection than G18 infection (P < 0.05)." (PMID 29263113, 2018). "In comparing the data from the two array experiments, we noted that the only cytokine found to be upregulated by 2-fold or more in both wild-type and sagA complemented infection compared to mock and SLS-deficient infection, respectively, was IL-1β." (PMID 30018884, 2018). "Neutrophils that rapidly infiltrate to the site of infection were found to produce IL-1β and IL-23 during OPC." (PMID 29782555, 2018). "Most of the pro-inflammatory markers, such as IL-1β and IL-6, were only detected at low concentrations in the different infection groups." (PMID 30619332, 2018). "As these in vitro studies indicated that Streptolysin S is a major contributor to IL-1β production during GAS infection of keratinocytes, we next sought to determine the physiological impacts of IL-1β production in an in vivo infection model." (PMID 30018884, 2018). "Prominent shifts in TAB1 and TAB2 proteins to a lower electrophoretic mobility were detected upon infection with H. pylori or stimulation with TNF or IL-1β." (PMID 29581850, 2018). "Interleukin-1 beta (IL-1β) is a pro-inflammatory cytokine, which is produced as an immune response to both injury and infection." (PMID 29973222, 2018). "In our study, we only found significant difference of TNF-α response in the 2000 CFU level of infection between the two strains, same as other cytokines including IL-4, IL-10, GM-CSF, IL-1β, IL-2, IL-6, IL-13, and IL-18." (PMID 30577452, 2018). "Accordingly, in kidney, TNFα, IL6 and IL‐1β mRNA levels were significantly reduced in p38γ/δ−/− and LysM‐p38γ/δ−/− mice at day 1 post‐infection, compared to WT mice." (PMID 29661910, 2018). "Indeed, infection caused upregulation of IL-6, TNFα and IL-1β, typically associated with classical activation, as well as of arginase and IL-10, which is linked to regulatory macrophages and may have profound suppressive effects on both innate and adaptive responses." (PMID 29579113, 2018). "Although not reaching statistical significance, average serum levels of TNF-α, KC/IL-8, G-CSF and IL-1β on day 3 post-infection where higher in BPSMΔprn- compared to BPSM-infected mice." (PMID 29559630, 2018). "Il1b, Nos2 (coding for iNOS) and Il6 were upregulated in infection, however, there was similar upregulation in both mouse strains." (PMID 30169526, 2018). "Taken together, these data showed that infection of THP-1 cells with GRA15-intact T. gondii produced IL-1β in a manner dependent on NLRP3 and caspase-1; this led to an indirect reduction in IDO1 proteins, thereby supporting parasite growth in human cells." (PMID 30301855, 2018).